IL13 (interleukin 13)
Diseases named in the same sentence as IL13 in open-access papers (continued):
Sharing a sentence is not in itself a finding about the gene and the disease.
nasal polyps (continued). "Studies on the regulation of mucin genes in response to cytokines reported that IL-4, IL-13, IL-8 IL-33, and TNF increase the mRNA and protein expression levels of MUC5AC in nasal polyp-derived epithelial cells." (PMID 33477617, 2021). "Indeed, the effect of IL-4/IL-13 and IL-5 on nasal epithelial repair was already showed but to date, no study has precisely described the role of IL-6, IL-9 and IL-10 (new ILs described in nasal polyposis) on human nasal epithelial cells in an in vitro wound repair model." (PMID 32209102, 2020). "In nasal polyps, IL-5 correlated highly with other Th2 cytokines: eotaxin, MCP-1, MCP-4, TARC, IL-4 and IL-13." (PMID 26132710, 2015). "Subsequently, a role for TSLP in activation of ILC2 was demonstrated as purified human peripheral blood and nasal polyp ILC2 cultured with TSLP and IL-33 displayed enhanced IL-4, IL-5, and IL-13 production above IL-33 alone." (PMID 24876829, 2013). "The exact pathophysiology of nasal polyposis is not completely explained, but recent studies demonstrated that it involves cytokines such as IL-5, IL-4 and IL-13." (PMID 35630042, 2022). "In nasal polyp tissue, S. aureus can directly induce the release of the epithelial cell-derived cytokines TSLP and IL-33 by binding to TLR 2, thereby potentially propagating the expression of type 2 cytokines IL-5 and IL-13 in nasal polyp tissue." (PMID 35878202, 2022). "Notably, it has been reported that SEB not only enhances Th2 response through interaction with TLR2 signaling but also plays a potential role in IL-5, IL-13, and RANTES production in dispersed nasal polyps following the development of CRSwNP." (PMID 30764556, 2019). "Surprisingly, the situation in nasal polyps tissue was different, since neither IL-13 nor IL-17 alone was correlated with an increase in pendrin expression." (PMID 30744098, 2019). "IL‐13, IL‐4Rα, IL‐13Rα1, and MUC5AC were found to be highly expressed in nasal polyp tissue from patients with eosinophilic chronic rhinosinusitis (ECRS), and IL‐13 expression was positively correlated with MUC5AC expression, indicating that IL‐13 can directly regulate mucin hypersecretion." (PMID 38282195, 2024). "Nasal polyp tissues showed significantly (P ≤ 0.01) altered gene expression values for over 4,000 genes and a significant increase of Th2 cytokines (IL-4, IL-5, IL-10, and IL-13) compared to the inferior turbinate (data not shown)." (PMID 24995349, 2014). "ST2 was over-expressed in ILCs from CRSwNP tissues compared with chronic rhinosinusitis without nasal polyp (CRSsNP), and ST2-positive ILCs were a source of IL-13 in response to IL-33." (PMID 38137606, 2023). "Polycytidylic acid (poly (IC)) is the ligand for TLR3, and exposure to poly (IC) selectively induces IL-10, but not IL-5, IL-13, IFN-γ or IL-17A, production by nasal polyp cells." (PMID 36003393, 2022).
parasitic infections (70 papers, 2006 to 2025). "Consistent with this is the fact that transgenic mice overexpressing IL-13 are highly susceptible to T. cruzi infection with enhanced parasitemia and impaired survival compared to wild-type mice (Dar and Hölscher, 2018)." (PMID 39119291, 2024). "A parasitic infection triggers the secretion of interleukins, particularly interleukin 25 (IL-25), which, in turn, causes the secretion of interleukin 13 (IL-13), which is responsible for goblet cell hyperplasia and mucin production." (PMID 34836095, 2021). "So far, we have shown that during experimental Chagas disease overexpression of IL-13 resulted in high Arg-1 expression and arginase activity that was associated with a decreased survival rate and enhanced parasitemia." (PMID 30555475, 2018). "IL-5 has been described as a Th2-cell cytokine whose expression is upregulated in inflammatory-associated conditions associated with parasitic infections, similar to IL-4 or IL-13, with secretion of IL-5 by astrocytes and microglia having been described." (PMID 26834537, 2015). "Elevated levels of IL-13 have been implicated in allergic responses and in parasitic infections." (PMID 23521898, 2013). "Because M2-macrophage activation is mediated by IL-4 and/or IL-13 (Th2-type cytokines), these macrophages are normally associated with immune responses that possess a Th2-skewed cytokine environment, as observed in parasite infections and allergic inflammation." (PMID 21731741, 2011). "Studies in which parasite infection was induced to combat allergic inflammation reported that parasite infection did increase IL-13 cytokine production." (PMID 40718495, 2025). "IL-4 and IL-13 play a critical role in allergic inflammation and parasite infection and act through the STAT6 signaling pathway." (PMID 39502090, 2024). "Polarization of M2 macrophages is stimulated by cytokines (such as IL-4, IL-10, and IL-13) and parasite infection." (PMID 39123188, 2024). "Similar to Th2 cells, ILC2s are elicited during parasitic infections and regulate tissue immunity and inflammation by producing Th2 cytokines (IL-4, IL-5- and IL-13) to recruit and activate eosinophils and alternatively activated macrophages." (PMID 39250522, 2024). "Other mechanisms promoting tuft cell development are possible; in the intestine, tuft cell hyperplasia following parasitic infection is dependent on IL-13–producing ILC2s." (PMID 38061015, 2024). "ILC2 can secrete IL-13 to promote mucus secretion by goblet cells, thus playing a crucial role in parasitic infections; this process is reliant on IL-33." (PMID 37686309, 2023). "The primary immune response against parasitic infections is type 2 immunity, which is characterized by the infiltration of mast cells, eosinophils, and basophils, and the release of cytokines such as IL-13, IL-5, IL-4, and IL-25." (PMID 37686309, 2023). "Although IL-13 is secreted by various cell types, including Th2 cells, ILC2s are the main producers of IL-13 in parasite infections, especially during the early phase." (PMID 37696896, 2023). "Our data is in agreement with previous reports of ILC2s in the intestine, where IL-25 produced by Tuft cells further activated these cells to produce IL-13 in a parasitic infection context." (PMID 35711429, 2022). "Th2 cells are critical for the control of certain parasitic infections through the production of the clustered group of cytokines IL-4, IL-10 and IL-13." (PMID 35215986, 2022). "In the steady state and after parasite infections, ILC2s produce growth factors of goblet cells, such as interleukin 13 (IL-13), in response to interleukin-25 (IL-25) secreted from Tuft cells." (PMID 34512636, 2021). "Both ILC2 and Th2 cells can be activated by IL-33, IL-25, and TSLP, and release type 2 effector cytokines (e.g., IL-5 and IL-13) during parasite infections, and thus, contribute to type 2 immunopathology." (PMID 33013869, 2020).
parasitic infections (continued). "Activated basophils express CD40 ligand and secrete IL-4 and IL-13, which are required for IgE class-switching and production during parasitic infection." (PMID 33335529, 2020). "ILC2 and CXCR6+ST2+ memory Th2 cells express IL-33 receptors and produce high concentrations of IL-5 and IL-13 during allergic responses and parasitic infections." (PMID 33335529, 2020). "Mucus production during parasite infections is under the immune control of type-2 cytokines, with interleukin-4 (IL-4), IL-13, and IL-22 altogether playing the major role in host protection." (PMID 31269896, 2019). "Alveolar or extrapulmonary macrophages produce IL-13 in response to rhinovirus or parasitic infection in mice." (PMID 27557561, 2016). "YM1, whose function is poorly understood, exists as a secretory protein transiently expressed in microglia/macrophages during hematopoiesis, during parasitic infection or after interleukin-4/interleukin-13 cytokine stimulation." (PMID 20846376, 2010). "In contrast to classically activated macrophages (M1), M2 are induced by Th2 cytokines IL-4 and IL-13, that are prevalent at parasitic infections and in wound settings." (PMID 18945374, 2008). "The TH2 phenotype is featured in responses to parasitic infections and is prominent in allergic responses, with IL-4, IL-5, and IL-13 as abundant cytokines." (PMID 16396683, 2006). "This cytokine, IL-13, subsequently acts on undifferentiated progenitor cells in the epithelial crypts, promoting their differentiation into tuft cells and goblet cells, thereby mediating immune responses to parasitic infections." (PMID 40356895, 2025). "When it comes to innate immunity, IL-33 potently stimulates innate lymphoid cells type 2 (ILC2s), facilitating their proliferation and secretion of type 3 cytokines such as IL-5 and IL-13, which are essential in responses to parasitic infections and allergic inflammation." (PMID 41284319, 2025). "IL-13 plays roles in stimulating the differentiation of Th2 cells and inhibiting the differentiation of Th1 cells, which are involved in the adaptive immune response to infection, including parasitic infection." (PMID 38393122, 2024). "During parasitic infection, IL-4 and IL-13 induce the Gsdmc1-4 expression in the intestine." (PMID 39489845, 2024). "In the gut, IL13 is produced by ILC2s in response to parasitic infection or tissue damage." (PMID 34350166, 2021). "These events have consequences on the adaptive immune responses, given that FhCL3-treated DCs promote a signature profile pattern of cytokines IFN-γ and IL-13 that could turn out to be protective in this parasitosis." (PMID 30967874, 2019). "During parasite infections both IL-4 and IL-13 are the major drivers of STAT6 translocation." (PMID 30619333, 2018). "Despite recent studies showing the importance of regulating IL-4Rα expression on CD4+ T cells following parasitic infection in vivo, only few studies have addressed how the cytokine receptors for IL-4/IL-13 are regulated on CD8+ T cells following virus infection in vivo." (PMID 23383283, 2013). "For example, the current pediatric population is naturally exposed to additional conditions such as other parasitic infections, which may independently alter IL-13 production." (PMID 23521898, 2013). "Indeed, dominated T helper type 2 responses in parasitic disease increased arginase expression by IL-4 and IL-13 signaling through the transcription factor STAT6." (PMID 21526166, 2011). "Finally, we show that the interaction of DCs with FhCL3 has consequences on adaptive immune response, since it confers a unique expression pattern of cytokines IFN-γ and IL-13 that could be protective in this parasitosis or in other helminth infections." (PMID 30967874, 2019).
parasitic infections (continued). "This was done to investigate the possibility that VV-WR infection induced IL-4 and/or IL-13 to up-regulate IL-4Rα expression on naïve bystander CD8+ T cells similar to what has been reported on naïve bystander CD4+ T cells responding to IL-4 following parasitic infection." (PMID 23383283, 2013). "At 8 d PI in baso IL-4/IL-13 (−) mice, FITC-dextran levels were positively correlated with parasitemia, plasma IL-1α, IFN-γ and IL-9, while bacterial 16S copies were positively correlated with plasma IFN-γ and IL-12p40." (PMID 38780542, 2024). "We demonstrated that even in the absence of symptomatic infections or asymptomatic urinary or parasitic infections, children with CZS have low CCL2 and CXCL8 production and increased serum levels of IFNγ and IL-13." (PMID 37766239, 2023). "In Mcpt4+/+ mice, parasitemia is the overwhelming focal point of the host immune response, with correlations between type 1 (IFN-γ) and type 2 (IL-10 and IL-13) cytokines and chemokines as well as MPO." (PMID 35154114, 2022). "In contrast, alternatively activated M2 macrophages play a pivotal role in immune suppression, wound healing, and fibrosis, and are induced by parasitic infections, immune-suppressive cytokines (e.g., IL4, IL10, IL13), and glucocorticoids." (PMID 36552868, 2022). "Cellular necroptosis and injury from parasitic infection stimulates the release of cytokines and alarmins that promote the production of type II polarizing (anti-inflammatory) cytokines including IL4, IL13, TGFβ, and IL10." (PMID 34350166, 2021). "Instead, mice lacking integrin αvβ8 expression on DCs displayed an early increase in production of the protective type 2 cytokine IL-13 by CD4+ T-cells, and inhibition of this increase by crossing mice to IL-4 knockout mice restored parasite infection." (PMID 24098124, 2013). "Previous studies had shown that parasitic infection with Nb induced the expression of AAM genes in Mac3+ macrophages in the lung suggesting that Mac3 (also known as CD107b and lysosomal-associated membrane protein 2, LAMP2) may also be induced by IL-4 and IL-13." (PMID 22292924, 2012). "The results indicated that the knockout of IL-13 or IL-4Rα significantly inhibited tuft cell expansion induced by parasitic infection, whereas the knockout of IL-4 did not have a notable effect." (PMID 40356895, 2025). "Bacterial 16S copy numbers were absent from the male, baso (−) network, and only IL-13 was directly and strongly negatively correlated with parasitemia in this network." (PMID 35970557, 2022). "It is typical that the anti-bacterial immune response promotes differentiation of CD4+ T cells into Th1 cells that produce IFN-γ and TNFα, as opposed to Th2 cells that produce IL-4 and IL-13 usually in response to parasitic infection or allergy." (PMID 34900999, 2021). "Surprisingly, we identified a unique CD4 T cell subset in the skin that was induced by both allergen priming in the skin and parasite infection in the lung that was committed solely to IL-13 expression and was completely independent of IL-4." (PMID 29910811, 2018). "Infected mice deficient in IL-13 or STAT6 did not reduce SFB or IL-17, and exogenous IL-25 replicated the effects of parasite infection in wild type mice." (PMID 26377648, 2015). "These other parasitic infections may (in the presence or absence of P. falciparum malaria) complicate IL-13 production in relation to other immune mediators." (PMID 23521898, 2013). "Interestingly, it has been shown that goblet cell hyperplasia may also occur in a Th2-independent manner without the influence of IL-4 and IL-13 in some parasitic infections, including Schistosoma mansoni." (PMID 33013869, 2020). "In baso IL-4/IL-13 (+) mice, FITC-dextran levels were positively correlated with MPO, NE, Mcpt1, and parasitemia in the main network, and bacterial 16S copies were negatively correlated with plasma IL-12p40, which was isolated from the main network." (PMID 38780542, 2024).
parasitic infections (continued). "The deviation is exacerbated by the three mice that succumbed to parasitemia during the first peak and did not have the opportunity for Th2 type responses, mediated by IL10, IL13, IL4, and IL6 to develop." (PMID 35634275, 2022). "We followed the number of IL-4- and IL-13-expressing CD4 T cells that appear in the draining lymph node and subsequent type 2 inflammatory response in the skin or lung following intradermal priming with allergen or parasite infection, respectively." (PMID 29910811, 2018).
viral infection (70 papers, 2009 to 2026). "IL-13 and amphiregulin contribute to the repair of tissue damage caused by helminthic and viral infections." (PMID 40872304, 2025). "We have previously shown that the type 2 cytokines IL-4 and IL-13 enhance the susceptibility of KC to viral infection." (PMID 37298195, 2023). "Previous observations by our group identified that KC have increased susceptibility to viral infection with VV after exposure to type 2 cytokines (IL-4 + IL-13)." (PMID 37298195, 2023). "Our group has also demonstrated that type 2 cytokines (IL-4 and IL-13) increase susceptibility to viral infection, further highlighting the complex interactions between the microbiome, host immune responses, and viral infection in AD." (PMID 37737609, 2023). "Several groups have demonstrated that KC exposed to the type 2 cytokines IL-4 and IL-13 have increased susceptibility to viral infection." (PMID 37298195, 2023). "Our findings support the hypothesis that unique cytokine signatures present in the skin, e.g., subjects with the greatest expression of IL-4, IL-13, and IL-22, would be at most risk of experiencing disseminated viral infections." (PMID 37298195, 2023). "Persistence of frequent exacerbations in PFE was associated with increased T1‐cell activation, IL‐13 overexpression and fibrosis pathways, with a reduced response to viral infections, providing some insight into the driving mechanism for the persistence of frequent exacerbations." (PMID 35474304, 2022). "Together, these results confirm at a protein level the downregulation and upregulation of ACE2 caused by IL-13 stimulation and virus infection of the airway epithelium, respectively, while also revealing ACE2 protein at the apical epithelial surface, particularly in ciliated cells." (PMID 33046696, 2020). "In addition, the production of inflammatory chemokines normally triggered by IL-13 and IL-17A, which are strongly linked to not only viral infection but also asthmatic condition, was reduced by the late addition of BUD." (PMID 32120846, 2020). "In addition, the production of inflammatory chemokines that were induced by not only viral infection, but also two cytokines strongly linked to asthmatic conditions, IL-13 and IL-17A, were reduced by BUD." (PMID 32120846, 2020). "However, these cells did express a higher amount of the T helper type 2 (TH2) cell–associated cytokines IL-5 and IL-13 at day 10 of viral infection in L. paracasei-administrated mice." (PMID 28931041, 2017). "Finally, mice deficient in IL-13 or STAT-6 were significantly more susceptible than WT animals in response to WT or mutant virus infection." (PMID 25751266, 2015). "TSLP is released from the airway epithelium in response to allergens, viral infection, and type 2 cytokines, and it activates dendritic cells and ILC2s to promote Th2 inflammation, positioning it upstream of the IgE, IL-5, and IL-13 pathways." (PMID 41487819, 2025). "Many recent studies have indicated that various viral infections can induce IL-13 production and lead to pathological tissue damage through different mechanisms." (PMID 38508309, 2024). "During viral infection of chickens, it was observed that an increase in the Th1 cytokine IFN-γ was linked to reduced expression of the Th2 marker interleukin-13 (IL-13) in both ileal tissue and the spleen." (PMID 39342330, 2024). "According to these authors, the concomitant secretion of IL-13 and antiviral interferons can decrease inflammation and injury due to the capacity of IL-13 in inhibiting the pro-inflammatory factors synthesis by monocytes and macrophages during viral infection." (PMID 35686128, 2022). "The type of viral infection was furthermore the biggest driver for differences in blood coagulation (r=0.39, p-value 2x10-07), cellular response to interleukin-13 (r=0.38, p-value 5x10-07)." (PMID 35663963, 2022).